PRDX1 (peroxiredoxin 1)
Diseases named in the same sentence as PRDX1 in open-access papers (continued):
Sharing a sentence is not in itself a finding about the gene and the disease.
tumor (continued). "Although this mechanism has been primarily described in macrophages, it suggests a broader regulatory role for PRDX1 in lipid metabolism and cholesterol homeostasis, which may be relevant in the context of tumor-associated metabolic reprogramming." (PMID 41019038, 2025). "Thus, it is predicted that arsenite will sensitize tumours to many other chemotherapeutic agents that act by damaging the DNA and more profoundly if the cancer cells are deficient in PRDX1 function." (PMID 40387816, 2025). "This close spatial association implies that PRDX1-positive monocytes and fibroblasts may shape the tumor microenvironment through reciprocal signalling, thereby influencing tumor progression." (PMID 40256656, 2025). "In addition, PRDX1 has been implicated in modulating the tumor immune microenvironment, facilitating immune escape through redox-dependent pathways." (PMID 41019038, 2025). "As such, we propose that small molecule inhibitors of PRDX1, or single nucleotide polymorphisms that compromise PRDX1 function, in combination with low doses of arsenite can be exploited to treat chemo-resistant tumours." (PMID 40387816, 2025). "Considering the pivotal role of DCs in activating anti-tumor T cells 49, further investigations into the association between PRDX1 and DC subtypes may offer novel strategies for DC-based anti-tumor therapy." (PMID 40303499, 2025). "Meanwhile, the level of PRDX1 expression linked positively with HCC tumor mutational burden (TMB)." (PMID 37842089, 2023). "They demonstrated that both recombinant Prdx1 and the supernatant from Prdx1-secreting tumor cells could cause these cells to secrete TNFα and IL-6." (PMID 35052630, 2022). "In addition, high PRDX1 expression was associated with large tumor size (OR = 1.69, 95% CI: 1.07-2.68, P = 0.025), advanced TNM stage (OR = 2.26, 95% CI: 1.24-4.13, P = 0.008), and poor tumor differentiation (OR = 0.59, 95% CI: 0.44-0.81, P = 0.001)." (PMID 33747258, 2021). "Furthermore, the role of PRDX1 in promoting tumor metastasis was associated with increased expression of Snail and MMP-9 and decreased expression of E-cadherin." (PMID 31956363, 2020). "The peroxirredoxins (Prdxs) are small proteins of sweep (scavening) of H2O2, that could prevent tumor development since the loss of Prdx1 in mice leads to premature death due to cancer." (PMID 27601940, 2016). "In order to further characterize and validate the identified tumor-associated protein Prdx1, recombinant Prdx1 protein was subsequently used as a target antigen to screen the anti-Prdx1 autoantibody in sera from patients with ESCC and normal individuals by ELISA and western blotting." (PMID 24009050, 2013). "Considering the protective effects of PRDX1 against oxidative damage at telomeres 67, 68, we speculated that the loss of PRDX1 in nucleus might lead to telomere crisis and genome instability which could promote tumor progression 69-71." (PMID 32231717, 2020). "Likewise, xenotransplanted PRDX1-deficient MCF-7 cells presented a retarded tumour growth." (PMID 30287919, 2018). "In contrast, the tumor-enriched PRDX1+ and HERPUD1+LA-Mac subtypes displayed mixed M1/M2 signatures, suggesting alternative activation states beyond the canonical M1/M2 classification." (PMID 41601657, 2026). "Building upon this, our study further demonstrates that the PRDX1+LA-Mac subtype represents a highly tumor-promoting macrophage population in KIRC." (PMID 41601657, 2026). "Our research has thus far concentrated solely on the role of RAI14, leaving the involvement of PRDX1 in RNASEH2C-mediated tumor regulation unclear." (PMID 41361104, 2025). "Functional validation through in vitro assays confirmed that PRDX1 modulates key enzymes involved in lipid metabolism, thereby contributing to tumor cell proliferation and oxidative stress resistance." (PMID 41019038, 2025).
tumor (continued). "The upregulation of PRDX1 and enhanced glycolytic activity provide not only the energy required for tumor proliferation but also immunosuppressive signals that facilitate tumor immune evasion." (PMID 40693141, 2025). "Our findings uncovered a novel role for PRDX1 in anti‐tumor immunity through the regulation of macrophage polarization." (PMID 41306557, 2025). "Tumours with low PRDX1/MRE11 co-expression have favorable PFS as well as overall survival (OS) compared to tumours with high PRDX1/MRE11." (PMID 40387816, 2025). "In vivo, bacterial infection decreased the antitumor efficacy of PD-1 blockade by 43% (tumor volume vs. control; p = 0.008), an effect that was reversed upon PRDX1 inhibition." (PMID 40693141, 2025). "PRDX1 is known to neutralise intracellular hydrogen peroxide, helping tumor cells survive under oxidative stress conditions." (PMID 40256656, 2025). "Further spatial transcriptomic analysis revealed the spatial heterogeneity of PRDX1 gene expression, with high expression concentrated in the tumor nest region and lower expression in the stroma." (PMID 40256656, 2025). "First, our functional validation was limited to in vitro assays, and in vivo studies such as xenograft models will be required to confirm the role of PRDX1 in tumor progression and therapeutic targeting." (PMID 41019038, 2025). "Our findings indicate that PRDX1-positive monocytes tend to be located adjacent to fibroblasts, suggesting their potential role in tumor-stroma interactions." (PMID 40256656, 2025). "Compared with celastrol, CP1 showed significantly stronger binding affinity to PRDX1 and more prominent antiproliferative activity against tumor cells." (PMID 40771925, 2025). "We found that PRDX1 deletion in macrophages reduced IL‐6 levels, thereby inhibiting tumor growth and enhancing antitumor immunity." (PMID 41306557, 2025). "In tumor biopsies, studies of other peroxiredoxins, such as peroxiredoxin 5 or peroxiredoxin 1 have demonstrated that their expression before any treatment is able to predict clinical outcomes." (PMID 41187427, 2025). "In conclusion, the molecular chaperone activity of PRDX1 to bind to CUL2 was at least as important as the peroxidase activity, providing new insights into the role of PRDX1 for drug design to inhibit CRC progression by modulating anti‐tumor immunity." (PMID 41306557, 2025). "By incorporating urine proteomic profiles, PRDX1 was identified as a pivotal biomarker, demonstrating robust predictive capacity, increased tumor expression, and correlation with unfavorable outcomes." (PMID 41019038, 2025). "Of these tumours, 130 out of the 183 were low for PRDX1 nuclear expression, and the other 53 showed high expression." (PMID 40387816, 2025). "In addition to its diagnostic and prognostic value, PRDX1+ malignant cells were found to exhibit enhanced stemness, increased intercellular communication, and enrichment of key oncogenic pathways, suggesting a potential role in maintaining aggressive tumor phenotypes." (PMID 41019038, 2025). "Spatial transcriptomics analysis uncovered heterogeneous expression of PRDX1 in the tumor nest regions, highlighting the spatial interaction between PRDX1-positive monocytes and fibroblasts." (PMID 40256656, 2025). "In the BRCA tumor microenvironment, PRDX1 is considered to play an essential role in immune cell regulation." (PMID 40256656, 2025). "Validation using the Xiantao Academic platform based on TCGA-LIHC RNA-seq data confirmed that PRDX1 expression was markedly higher in tumor tissues compared to adjacent normal liver tissues." (PMID 40693141, 2025). "We demonstrate that Bacilli infection leads to the upregulation of PRDX1, which activates glycolytic pathways and suppresses NK cell activity, thereby facilitating tumor immune evasion." (PMID 40693141, 2025).
tumor (continued). "Taken together, these results indicate that PRDX1‐KO macrophages exhibited enhanced phagocytosis and consequently suppressed tumor cell proliferation and migration in a co‐culture system." (PMID 41306557, 2025). "Studies have shown that down-regulation of PRDX1 significantly inhibits the growth rate of BC cells, and in vivo, PRDX1-deficient MCF-7 cells exhibit delayed tumor growth upon transplantation." (PMID 40496857, 2025). "In the case of cytoplasmic expression, 147 out of the 183 tumours were low for PRDX1 expression and 36 tumours exhibited high expression." (PMID 40387816, 2025). "Whereas other studies demonstrated that PRDX1 promoted tumor progression and metastasis through the activation of c-Jun, AP-1, and epithelial-mesenchymal transition in prostate, pancreatic, and colorectal cancers." (PMID 40825764, 2025). "Peroxiredoxin 1 (PRDX1) is an antioxidant enzyme overexpressed in several cancers that protects tumor cells from oxidative damage by scavenging excess reactive oxygen species making it a potential strategy for cancer therapy." (PMID 40771925, 2025). "In certain cancers, such as breast and lung cancer, PRDX1 has been shown to function as a tumor suppressor by inhibiting c-Myc activity and the PTEN/AKT pathway." (PMID 40825764, 2025). "To further elucidate the tumor-promoting mechanism of PRDX1, we used functional enrichment analysis to uncover its multi-pathway regulatory network." (PMID 40303499, 2025). "Reciprocally, PRDX1 ablation in macrophages restrains M2 polarization and enhances T‐cell‐mediated anti‐tumor immunity by promoting the secretion of inflammatory factors (IL‐1β and TNFα) via activation of JAK‐STAT1/NF‐κB signaling pathways." (PMID 41306557, 2025). "PRDX1-positive monocytes exhibit significant intercellular communication activity and immune regulatory functions in the tumor microenvironment, and their gene expression profile can be used to construct an effective survival prediction model for BRCA." (PMID 40256656, 2025). "The expression of PRDX1 exhibits significant spatial heterogeneity, with a higher concentration in the tumor nest region and relatively lower expression in the stromal region." (PMID 40256656, 2025). "For instance, PRDX1 suppresses ferroptotic cell death by scavenging lipid peroxides, thereby promoting tumor cell survival under oxidative stress." (PMID 41019038, 2025). "Overall, PRDX1 plays a crucial role in tumor cell survival, metastasis, immune evasion, and chemotherapy resistance, making it a potential target for cancer treatment and immunotherapy." (PMID 40256656, 2025). "Immunohistochemistry results obtained from the Human Protein Atlas (HPA) database further illustrated the spatial expression patterns of PRDX1 in tissue samples, corroborating its upregulation in tumor tissues." (PMID 41019038, 2025). "The tumor suppressive role of PRDX1 has been particularly evident in breast and lung cancer models using these knockout mice." (PMID 39720522, 2024). "Western blot analysis showed that the protein levels of NRF2 and GPX4 in xenograft tumor tissues were significantly reduced by downregulating PRDX1." (PMID 39430237, 2024). "The study also revealed that peroxiredoxin 1 (PRDX1), an essential component of the antioxidant defense system, is deficient in NK cells within the tumor microenvironment." (PMID 37469162, 2024). "LAMP2a degradation leads to the promotion of tumor-activating macrophages by degrading peroxiredoxin 1 (PRDX1) and CREB-regulated transcription coactivator 1 (CRTC1)." (PMID 38370407, 2024). "Conversely, inhibiting the activation of JNK1 signaling by reducing H2O2 levels using the peroxidase PRDX1 effectively mitigated breast fibroblast invasion and tumor development." (PMID 37469162, 2024). "Taken together, our results demonstrated that clones in the same tumor can naturally express less PRDX1, MITF, SOX10, PGC-1α, and pigmentation markers." (PMID 38790661, 2024).
tumor (continued). "Here, we provide evidence that low PRDX1 expression in tumours can be a biomarker for arsenite regimen response." (PMID 38067110, 2023). "Further, knockdown of PRDX1 attenuated the inhibition effects of Celastrol or compound 19-048 treatment on tumor growth." (PMID 36732502, 2023). "IHC analysis further confirmed significantly higher Prdx1 expression in human OSCC tissues compared to adjacent non-tumor tissues." (PMID 38007535, 2023). "From ESTIMATE algorithm analysis results, the immunological score and estimated score (tumor purity) of HCC patients with PRDX1 high expression were relatively high than those with low expression." (PMID 37842089, 2023). "PRDX1, by modulating the HEF1/Aurora A/HDAC6 signaling pathway, fosters the loss of primary cilia, contributing to ESCC tumorigenesis and tumor growth." (PMID 37781072, 2023). "Depending on the tumor type and the stage of progression, PRDX1 can either inhibit or promote cancer growth." (PMID 37566013, 2023). "Currently, most research on PRDX1 focuses on tumors, where it regulates tumor cell proliferation and apoptosis in vitro in several ways." (PMID 37227568, 2023). "Our results indicated that Prdx1 is overexpressed in tumor tissues and cell lines of OSCC and plays a crucial role in supporting cell proliferation and mobility by reducing excessive ROS." (PMID 38007535, 2023). "The results showed that Celastrol and compound 19-048 suppressed the overall tumor progression of SW620-gNS xenografts with decreasing tumor size, and PRDX1 knockdown group showed similar effect." (PMID 36732502, 2023). "Tumor bearing lean mice had low expression of Prdx1, while the high fat diet fed obese mice had a high expression of Prdx1." (PMID 35816618, 2022). "Prdx1, a target factor of Nrf219, acts as a molecular chaperone to protect tumor cells from apoptosis by inhibiting JNK1 activation." (PMID 35027562, 2022). "The tumor growth was determined as well, and the binding relation between miR-431-5p and PRDX1 was confirmed." (PMID 35460420, 2022). "PRDX1 is a 23-kDa stress-triggered macrophage redox protein that has been addressed to be related to tumor metastasis, angiogenesis, and inflammation in CRC." (PMID 35460420, 2022). "We further show that both high fat as well as treatment with Q upregulated PRDX1, an antioxidant protein that protects tumor cells from chemotherapy induced oxidative stress." (PMID 35816618, 2022). "The reduced anti-tumor potential of NK cells was correlated with intrinsically low expression of peroxiredoxin-1 (PRDX1), whereas its overexpression improved NK-cell function." (PMID 35163421, 2022). "Collectively, these results support the tumor-promoting effect of ROS and PRDX1 and reveal one of the pathways by which CRC cells maintain homeostasis under metabolic stress." (PMID 33712558, 2021). "PRDX1, known as one member of peroxiredoxin family, has been demonstrated to have tumor-promoting and apoptosis-inhibiting role in several types of cancer." (PMID 33712558, 2021). "The overexpression- and tumor-promoting effects of PRDX1 have been described in numerous types of human cancer." (PMID 33712558, 2021). "Moreover, MMP could be activated by PRDX1 to cause tumor cell metastasis." (PMID 33747258, 2021). "Several studies have showed that Prdx1 promotes tumor occurrence mainly by adjusting the levels of ROS, TGF-β1, mTOR/p70S6K, and ROS/ERK/cyclin D1." (PMID 32357862, 2020). "Exogenous overexpression of PRDX1 significantly promoted tumor growth, whereas the growth of the tumor was severely suppressed by knockdown of PRDX1 in SiHa cells." (PMID 31956363, 2020). "Collectively, we proposed that PRDX1 promoted tumor cell proliferation probably through regulating Nanog and PCNA expression." (PMID 31956363, 2020). "On the contrary, PRDX1 was also confirmed to be a tumor suppresser by protecting PTEN from oxidation-induced inactivation." (PMID 31956363, 2020).
tumor (continued). "The tumor suppressor function of PRDX1 was also demonstrated in another study using a different Prdx1-knockout mouse strain, which was generated using the Lexicon gene trap ES cell clone, which has a gene trap vector in intron 3 of the Prdx1 gene." (PMID 32098329, 2020). "The inhibition of Prdx1 expression promoted cilia regeneration and inhibited the invasion of tumor cells." (PMID 32357862, 2020). "PRDX1 was found abundantly expressed in tumor tissues, while was rarely expressed in paired adjacent non-tumor tissues." (PMID 31956363, 2020). "On the contrary, knockdown the expression of PRDX1 in SiHa cells resulted in a significant decrease in tumor weight." (PMID 31956363, 2020). "Using the same knockout mice, Neumann’s group indicated that PRDX1 is involved in Pten-mediated tumor suppression in Ras-induced breast cancer and inhibition of fibroblast transition into cancer-associated fibroblasts (CAFs)." (PMID 32098329, 2020). "The results showed that the formation of tumor cell cilia was significantly increased following Prdx1 inhibition compared with this process in the control group." (PMID 32357862, 2020). "We also showed that the expression of Prdx1 regulates the action of the HEF1-Aurora A-HDAC6 signaling axis to promote the disassembly of primary cilia, and suppression of Prdx1 results in decreased tumor formation and tumor mass volume in vivo." (PMID 32357862, 2020). "In nude mice, the tumor formation capacity, the tumor volume, and tumor weight were significantly decreased after inhibition of Prdx1." (PMID 32357862, 2020). "Genes related to the formation of cellular protrusions (cilia) were significantly activated, and genes influencing the invasion of tumor cells (cell movement of the carcinoma cell line) were significantly inhibited after the inhibition of Prdx1." (PMID 32357862, 2020). "The expression of PRDX1 in tumor tissue was significantly higher than that in normal oral mucosa, as determined by IHC." (PMID 31429766, 2019). "At the cellular level, tumor cells were positive for PRDX1, an ROS scavenging enzyme that is the molecular target of Ade." (PMID 31533285, 2019). "LINC00460 expression in HNSCC was correlated with lymph node metastasis and pathological differentiation, while PRDX1 expression was correlated with tumor size." (PMID 31429766, 2019). "Peroxiredoxin-1 is well known to play an important role in maintaining the ROS level for tumor development." (PMID 30917517, 2019). "NG2/CSPG4+ tumor cells revealed upregulation of peroxiredoxin-1 (PRDX-1), and were resistant to ionizing radiation; the knockdown of PRDX-1 slowed cell growth and sensitized to radiation." (PMID 30213051, 2018). "Two independent cohorts of patients showed high level of PRDX1 correlated with clinicopathological features such as larger tumor size and advanced tumor metastasis stage." (PMID 29492195, 2018). "PRDX1 level highly correlated with clinicopathological variables, including tumor size, presence of pathological facture, and malignant grade." (PMID 29492195, 2018). "One of the theoretical possibilities of tumour-specific downregulation of PRDX1 is the conjugation of anti-PRDX1 siRNA with a tumour-specific targeting agent, e.g., an antibody (reviewed in40)." (PMID 30287919, 2018). "Peroxiredoxin-1 (Prx1) is frequently elevated in many solid tumors and TME and is often associated with tumor growth and drug resistance." (PMID 29535842, 2018). "To determine if mRNA expression of Prdx1 and its transcriptional regulators (Nrf1, Nrf2) is elevated in patients, we searched the Oncomine mRNA database of normal and tumor pancreatic tissue." (PMID 29190947, 2017). "This implies that pTyr-Prdx1 in KC mice is more post-translationally modified than pTyr-Prdx1 in EL-Kras mice and less capable of performing its normal tumor suppressive antioxidant functions." (PMID 29190947, 2017).